FGF19 (fibroblast growth factor 19)
Diseases named in the same sentence as FGF19 in open-access papers (continued):
Sharing a sentence is not in itself a finding about the gene and the disease.
hepatoblastoma (continued). "Furthermore, the gene expression analysis of hepatoblastoma tumors uncovered that the high expression of FGF19 signaling pathway components as well as the low expression of FGF19 signaling repression targets correlates with the aggressiveness of the tumors." (PMID 27382436, 2016). "To gain insight into cytokine signaling in hepatoblastoma, we employed mass spectrometry to analyze the proteins secreted from Hep293TT hepatoblastoma cell line we established and identified the specific secretion of fibroblast growth factor 19 (FGF19), a growth factor for liver cells." (PMID 27382436, 2016). "Furthermore, blocking FGF19 signaling by an FGF receptor kinase inhibitor suppressed hepatoblastoma growth." (PMID 27382436, 2016). "Notably, FGF19 is amplified in a small percentage of hepatoblastomas." (PMID 40684183, 2025). "Since FGF19 expression colocalized to a subset of cells within the embryonal components of hepatoblastoma that showed high levels of both nuclear β-catenin and Wnt target gene expression, we asked whether the upregulation of FGFs in these tumoroids depended on β-catenin." (PMID 39567523, 2024). "Finally, we determined whether FGF19 expression in HB15 and HB17 depends on the biliary transcriptional program, as FGF19 expression was found in a subset of the SOX4-expressing embryonal hepatoblastoma cells with cholangiocytic features." (PMID 39567523, 2024). "A cholangiocyte-like subpopulation expresses FGF19, in a SOX4-dependent, paracrine manner, to drive the proliferation of neighboring embryonal hepatoblastoma cells." (PMID 40684183, 2025). "However, the role of FGF19 in childhood hepatoblastoma is unknown." (PMID 27382436, 2016). "As a control, spatial transcriptomic analyses of a section of normal liver from a patient with hepatoblastoma showed very low expression of FGF19, AXIN2, and SOX4, without apparent co-localization." (PMID 39567523, 2024). "These cholangiocyte-like cells are surrounded by embryonal hepatoblastoma cells, characterized by intermediate levels of WNT/b-catenin signaling, a high proliferation index (Ki67), and high expression of KLB, a hepatocyte transmembrane protein that plays a crucial role as a co-receptor for FGF19." (PMID 40684183, 2025). "Importantly, our data indicate that silencing FGF19 signaling by FGF19 shRNAs, anti-FGF19 neutralizing antibody, or an FGF receptor kinase inhibitor, LY2874455, inhibits the growth of hepatoblastoma cells, suggesting that FGF19 is a critical autocrine growth factor for hepatoblastoma." (PMID 27382436, 2016).
Hypercholesterolemia (4 papers, 2020 to 2023). An increased concentration of cholesterol in the blood. "Recent research has demonstrated that patients with hypercholesterolemia have elevated fibroblast growth factor 19 (FGF19), which is positively correlated with pro-atherogenic ceramide levels." (PMID 37111068, 2023). "Our obese rats were characterized by increased calorie consumption and body adiposity, hypercholesterolemia, elevated levels of liver enzymes and FGF-21, while the level of FGF-19 was reduced." (PMID 36362225, 2022). "We detected hypomethylation in FGF19 and FGFR1 genes in leukocytes DNA of obese patients with hypercholesterolemia." (PMID 33028190, 2020).
inflammatory bowel disease (4 papers, 2017 to 2026). A spectrum of small and large bowel inflammatory diseases of unknown etiology. "FGF-19 has been shown to exhibit anti-inflammatory effects, with studies indicating lower levels of FGF-19 in Inflammatory Bowel Disease (IBD), resulting from intestinal inflammation, compromised barrier function, and impaired bile acid absorption." (PMID 39205680, 2024). "The majority of patients with PSC have concomitant inflammatory bowel disease (IBD) and one may question if, in that setting, proper control of bile salt synthesis by the FXR/FGF19 axis is maintained." (PMID 27696157, 2017).
osteoporosis (4 papers, 2020 to 2025). A condition of reduced bone mass, with decreased cortical thickness and a decrease in the number and size of the trabeculae of cancellous bone (but normal chemical composition), resulting in increased fracture incidence. "Since being initial discovery, FGF19 has been proposed as a candidate gene for bone diseases because of the region of the FGF19 gene on the chromosome associated with osteoporosis-pseudoglioma syndrome." (PMID 37454120, 2023). "The FGF19 levels were lower in the osteoporosis and osteopenia groups (5105.0±2567.1 and 4915.1±2413.2 pg/mL, respectively) than in the healthy control group (7107.7±4240.1 pg/mL; p=0.006 and 0.016, respectively)." (PMID 32187280, 2020). "The bile acid and FGF19 levels were significantly lower in patients with postmenopausal osteoporosis than in healthy controls." (PMID 32187280, 2020). "The action of FGF19 on bone remains unclear, particularly in the context of osteoporosis or osteosarcopenia." (PMID 41185883, 2025). "In addition, studies have found that the FGF19 levels are significantly lower in postmenopausal patients with osteoporosis than in healthy women and are positively correlated with bone mineral density (BMD)." (PMID 35574015, 2022). "Additionally, our team has just reviewed FGF19’s function and therapeutic potential in skeletal development and diseases, describing its potential physiological role in cartilage and endochondral ossification, and its role in bone diseases including Apert syndrome, osteoarthritis, and osteoporosis." (PMID 37454120, 2023). "divided 150 postmenopausal Chinese women into osteoporosis group, osteopenia group, and healthy control group based on their BMD, and assessed serum bile acid, FGF19, and bone turnover biomarker levels." (PMID 35574015, 2022).
type 1 diabetes (4 papers, 2021 to 2026). "So we assumed that there were some associations between serum FGF19 and sklotho in children with type 1 diabetes." (PMID 36927328, 2023). "Consistent with our studies, previous studies found decreased serum fibroblast growth factor 19 level was a risk factor for type 1 diabetes newly diagnosed T1D patients." (PMID 36927328, 2023). "The post hoc analysis also revealed a notable difference in the FGF-19 concentration between the control group and patients with type 1 diabetes (p < 0.001)." (PMID 40943671, 2025). "And 66 type 1 diabetes participants were divided into two groups according to T1D duration or three groups according to HbA1c.Furthermore,we compared the serum levels of FGF19 and VEGF and sklotho in different groups." (PMID 36927328, 2023). "Furthermore, the concentration of FGF-19 was significantly lower in both study groups compared to the control group, with the lowest concentration found in patients with type 1 diabetes." (PMID 40943671, 2025). "We hypothesized that there were some associations between serum FGF19 and VEGF in children with type 1 diabetes, but the relationship between them was unclear." (PMID 36927328, 2023). "FGF19 may be involved in the development of complications in children with type 1 diabetes through interaction with VEGF and sklotho." (PMID 36927328, 2023). "Fibroblast growth factor 19 (FGF19) takes part in maintaining the balance of glycolipids and may be involved in complications of type 1 diabetes(T1D) in children." (PMID 36927328, 2023). "Our results suggest that children with type 1 diabetes have significantly lower FGF19 and soluble klotho concentrations and higher VEGF concentrations compared to healthy individuals, especially in individuals with the worst metabolic control, being expressed as high HbA1c levels." (PMID 36927328, 2023). "However, we demonstrated that 4th ventricular administration of FGF19 also decreases blood glucose in type 1 diabetic (T1DM) mice, suggesting the hindbrain as an underappreciated target tissue for this system." (PMID 34858337, 2021). "In a mouse model of type 1 diabetes (T1DM), FGF19 consistently and robustly increased action potential-dependent excitatory synaptic transmission to the DMV." (PMID 34858337, 2021). "This study reports the significantly lower levels of FGF19 and sklotho in children with type 1 diabetes, and higher level of VEGF, correlated with HbA1c, but not with the lipid concentrations nor the duration of the disease." (PMID 36927328, 2023).
biliary atresia (3 papers, 2022 to 2024). A rare, biliary tract disease characterized by progressive obliterative cholangiopathy of the intra- and extrahepatic bile ducts, occurring in the embryonic/ perinatal period, leading to severe and persistent neonatal jaundice and acholic stool. "Additionally, studies revealed that the expression of FGF19 in the liver tissue of patients with biliary atresia or PBC was significantly higher than FGF19 in serum, suggesting that intrahepatic auto-/paracrine FGF19 feedback signaling might exist." (PMID 39030473, 2024).
Central obesity (3 papers, 2019 to 2026). "It seems that FGF21, FGF19 and β-klotho concentrations are correlated with risk factors for metabolic diseases especially in subjects with abdominal obesity." (PMID 31151464, 2019). "Central obesity was associated with increased Klotho levels [156.4 pg/ml vs 118.5 pg/ml, p = 0.0275] and FGF21 levels [93.0 pg/ml vs 70.1 pg/ml, p = 0.0193] as well as a decrease in FGF19 levels [160.6 pg/ml vs 229.4 pg/ml, p = 0.0264]." (PMID 32546231, 2020).
gallbladder carcinoma (3 papers, 2017 to 2023). "The subclone of undifferentiated components contained FGF19 and MET amplifications that is not found in the tubular component and is reported to be associated with poor prognosis in liver and gallbladder carcinomas." (PMID 32487254, 2020). "A recent Japanese study showed that FGF19 gene amplification is detected in 3% of the overall BTC patient population (260 cases, including 145 iCCA), and it was more frequently observed in iCCA compared with extrahepatic CCA and gallbladder cancer." (PMID 28445152, 2017).
gallstones (3 papers, 2009 to 2025). Solid crystalline precipitates in the biliary tract, usually formed in the gallbladder, resulting in the condition of cholelithiasis. "Our findings suggest that individuals with FGF19 deficiency may be at increased risk of gallstone formation, a speculation that requires confirmation by clinical studies." (PMID 29876009, 2018). "Alternatively, loss of gallbladder function because of the presence of gallstones, or cholecystectomy could change the daily secretion pattern of FGF19 with the subsequent modification of the circadian rhythm of CYP7A1 mRNA." (PMID 19995447, 2009). "Patients with gallstones developed biliary stones as a result of insufficient increase in bile acid production by FGF19." (PMID 39950129, 2025).
gastric cancer (3 papers, 2022 to 2026). A primary or metastatic malignant neoplasm involving the stomach. "FGF19 was significantly associated with depth of invasion, lymph node metastasis, and TNM stage in gastric cancer." (PMID 36503378, 2022).
Hyperinsulinemia (3 papers, 2013 to 2022). An increased concentration of insulin in the blood. "Lipid and insulin synergistically increased FGF21 in healthy and insulin resistant women with PCOS; hyperinsulinemia suppressed FGF19 in controls." (PMID 33101202, 2020). "Moreover, one study showed that insulin stimulated FGF21 expression during hyperinsulinemic clamp in obese T2DM patients, while the other study demonstrated that acute hyperinsulinemia tended to decrease FGF19 levels in healthy and T2DM subjects." (PMID 24260557, 2013). "Overall, these data suggest that FGF19 and FGF21 may have a modulatory role in lipid and insulin metabolism as shown by hyperinsulinemia and the lipid infusion." (PMID 33101202, 2020). "Alternatively, the altered expression of FGF19 and/or FGF21 may be involved in a complex adaptive response to these diseases, or a phenomenon reminiscent of hyperinsulinemia and insulin resistance." (PMID 24260557, 2013).
Hypoglycemia (3 papers, 2021). A decreased concentration of glucose in the blood. "Notable, bile acids have been suggested to be involved in the pathogenesis of postprandial hypoglycemia via the bile acids-GLP-1-insulin-axis or indirectly via stimulation of FGF-19." (PMID 34084153, 2021). "In addition, we investigated the modulatory effects of exogenous (CDCA) and endogenous bile acids (by COL administration) on meal-induced plasma concentrations of glucose, including the risk of hypoglycemia, and other glucoregulatory hormones including insulin, glucagon, CCK, neurotensin and FGF-19." (PMID 34084153, 2021).
irritable bowel syndrome (3 papers, 2018 to 2023). Irritable bowel syndrome (IBS) is a chronic functional condition of the lower gastrointestinal (GI) tract characterized by abdominal pain or discomfort and disordered bowel habit (diarrhea, constipation, or fluctuation between the two). "In FGF19 deficiency, diarrhea resulting from bile acid spillage into the colon mimics irritable bowel syndrome." (PMID 29876009, 2018). "Additionally, the elevated level of some secondary BAs (free and conjugated UDCA, 7-KDCA, etc.)in gut promoted the synthesis and excretion of BAs with irritable bowel syndrome patientsby inhibiting intestinal FXR/ FGF19 signaling pathway, which was beneficial to maintain in vivo glucose homeostasis." (PMID 37533083, 2023).
lipid metabolic disorder (3 papers, 2022 to 2025). "Furthermore, treatment with the antioxidant resveratrol (RSV) and its nanoformulation (RSV-NPs) markedly inhibited tumor growth in mice with lipid metabolic disorders, highlighting their potential to counteract progesterone resistance by disrupting this OLR1/FOXM1/FGF19 axis." (PMID 41270216, 2025).
osteoarthritis (3 papers, 2023 to 2025). A noninflammatory degenerative joint disease occurring chiefly in older persons, characterized by degeneration of the articular cartilage, hypertrophy of bone at the margins and changes in the synovial membrane. "Moreover, since FGF19 signaling may hinder cartilage regeneration, modulating its activity could also benefit the treatment of degenerative joint diseases such as osteoarthritis." (PMID 40765829, 2025). "Although circulating inflammatory proteins may not mediate the occurrence of osteoarthritis resulting from skeletal muscle loss, this study found that high levels of CCL23, LAP-TGF-β1, and LIFR might contribute to reduce the risk of KOA, while high levels of FGF19 might increase the risk of KOA." (PMID 38811889, 2024).
polycystic ovary syndrome (3 papers, 2022 to 2026). A disorder that manifests as multiple cysts on the ovaries. "This study investigated the roles of FGF19 in polycystic ovary syndrome (PCOS) and its associated molecular mechanisms, specifically focusing on the FGFR4-ERK-NRF2 pathway." (PMID 40950398, 2025).
serous ovarian cancer (3 papers, 2024 to 2026). "Moreover, the FGF19/FGFR4 axis was correlated with poor prognosis in advanced high-grade serous ovarian cancer." (PMID 38273381, 2024).
acute liver failure (2 papers, 2016 to 2017). Rapid deterioration of liver function causing encephalopathy and coagulopathy. "Animal studies indicate that Fxr agonism can accelerate liver regeneration after PHx, while the FXR–regulated enterokine FGF19 can reduce mortality in a surgical model of acute liver failure." (PMID 27048617, 2016).
alcohol (2 papers, 2022 to 2024). "Currently, many clinical trials are evaluating the efficacy of different treatments involving the gut–liver axis, including FMT, drugs (eg, anti-alcoholism drug disulfiram), diet, probiotics, synbiotics, antibiotics, fibroblast growth factor 19 analog (aldafermin or NGM282), and physical activity." (PMID 38283696, 2024). "The authors held that fibroblast growth factor 19 - fibroblast growth factor receptor 4 (FGF19-FGFR4) pathway, which was target of lenvatinib, were involved in the tumorigenesis of non-alcoholic steatohepatitis- and alcohol-associated HCC and consequently, these HCCs responded better to lenvatinib." (PMID 36483039, 2022).
diabetic cardiomyopathy (2 papers, 2022 to 2023). Diabetic cardiomyopathy is a disorder of the heart muscle in people with diabetes. "Otherwise, FGF19 could protect oxidative stress-induced diabetic cardiomyopathy via activation of AMPK/NRF2/HO-1 pathway." (PMID 35847588, 2022). "FGF19 showed better mitochondrial efficiency, which may be related to higher cardiac contractility in the diabetic heart, and the modulation of PGC-1a, responsible for FGF19 activation, may be a therapeutic target for diabetic cardiomyopathy." (PMID 36927328, 2023).
esophageal adenocarcinoma (2 papers, 2019 to 2020). A malignant tumor with glandular differentiation arising predominantly from Barrett mucosa in the lower third of the esophagus. "Use case – Esophageal adenocarcinoma with reported amplification ofCCND1,MAP2K1,RICTOR,FGF10,FGF19,FGF3,FGF4 andMCL1." (PMID 31608148, 2019).
gestational hypertension (2 papers, 2022 to 2025). "The independent association between FGF-19 and SBP may thus suggest a role of FGF-19 in gestational hypertension, but this potential relationship needs to be elucidated in further studies." (PMID 35566542, 2022). "All the studies discussed suggest that FGF-21, FGF-19 and FGF-23 may play an important role in fetal and neonatal growth and development, particularly in pregnancies complicated by metabolic disorders, such as GDM or gestational hypertension." (PMID 40648894, 2025).
glucose metabolic disorders (2 papers, 2020). "Previous studies have shown that FGF19 has an insulin-like regulatory function in metabolism, and a low FGF19 concentration or impairment in FGF19 signaling can lead to glucose metabolism disorders in insulin-resistant and T2DM patients." (PMID 32104677, 2020). "Their role in maintaining glucose metabolism has been highlighted by animal studies where the administration of exogenous FGF-19 has been shown to prevent the development of glucose metabolic disorders in mice fed with a high-fat diet." (PMID 31998807, 2020).
hyperthyroidism (2 papers, 2014 to 2016). Overactivity of the thyroid gland resulting in overproduction of thyroid hormone and increased metabolic rate. "Additionally, in our study, for we can hardly recruit adequate subjects to investigate the changes of serum FGF19 concentrations in patients with hyperthyroidism, more research is now needed to better understand the relationship of FGF19 with thyroid." (PMID 27684859, 2016). "Fourth, serum FGF19 levels were clearly reduced in hyperthyroidism." (PMID 25172631, 2014). "Again, in contrast to hyperthyroidism, FGF19 levels were unaltered following eprotirome treatment." (PMID 25172631, 2014). "Hyperthyroidism, but not eprotirome treatment, markedly increased bile acid synthesis and reduced fibroblast growth factor (FGF) 19 and dietary cholesterol absorption." (PMID 25172631, 2014).
liver cirrhosis (2 papers, 2020 to 2024). "In PICRUSt analysis, MAM in the ascending colon in the liver cirrhosis (LC) group showed compromised functions associated with the intestinal barrier and bile acid production, and FGF19 expression was markedly decreased in the terminal ileum biopsy tissue in the LC group." (PMID 38650735, 2024).
lung fibrosis (2 papers, 2019 to 2024). "Therefore, FGF19 may possess resistance against pulmonary fibrosis and hold potential therapeutic implications for IPF." (PMID 39267721, 2024).
lymph node metastasis (2 papers, 2022 to 2024). "Other genes showing high fold change were FGF19 (highest 14.4 in a lymph node metastasis sample), CCND1 (highest 14.3 in a lymph node metastasis samples), and EGFR (highest 11,0 in a tumor sample)." (PMID 39324009, 2024).